SLC7A3 (solute carrier family 7 member 3)
Description:
Uniporter that mediates the uptake of cationic L-amino acids such as L-arginine, L-lysine and L-ornithine. The transport is sodium ions- and pH-independent, moderately trans-stimulated and is mediated by passive diffusion.
Synonyms: CAT-3; CAT3; ATRC3; FLJ14541
Tractability: Antibody: its Gene Ontology location is reachable by antibodies, with high confidence; UniProt places it where antibodies can reach, with medium confidence; UniProt predicts a signal peptide or a membrane-spanning region. PROTAC: ubiquitination databases record sites on it.
Gene: Protein-coding gene on chromosome X (70,925,575 to 70,931,149, reverse strand). Ensembl gene ENSG00000165349.
Subcellular location: Cell membrane
Pathways (Reactome):
Transport of small molecules: Amino acid transport across the plasma membrane
Gene Ontology:
Molecular function: L-arginine transmembrane transporter activity; L-lysine transmembrane transporter activity; L-ornithine transmembrane transporter activity; protein binding; amino acid transmembrane transporter activity; basic amino acid transmembrane transporter activity; transmembrane transporter activity
Biological process: L-arginine import across plasma membrane; L-lysine import across plasma membrane; L-ornithine import across plasma membrane; amino acid transport; transport across blood-brain barrier; amino acid import across plasma membrane; L-lysine transmembrane transport; ornithine transport; transmembrane transport
Cellular component: plasma membrane; membrane
Homologues: Orthologues: chimpanzee SLC7A3 (99% identical), macaque SLC7A3 (97% identical), pig SLC7A3 (89% identical), dog SNX12 (89% identical), guinea pig SLC7A3 (86% identical), rabbit SLC7A3 (85% identical), mouse Slc7a3 (82% identical), rat Slc7a3 (75% identical), zebrafish slc7a3a (65% identical), tropical clawed frog slc7a3 (63% identical), zebrafish slc7a3b (63% identical), Drosophila melanogaster CG7255 (47% identical), and 10 more. Paralogues in human: SLC7A1 (59% identical), SLC7A2 (57% identical), SLC7A14 (44% identical), SLC7A4 (42% identical), SLC7A8 (21% identical), SLC7A7 (20% identical), SLC7A6 (19% identical), SLC7A10 (19% identical), SLC7A11 (19% identical), SLC7A5 (19% identical), SLC7A9 (18% identical), SLC7A13 (16% identical).
Diseases named in the same sentence as SLC7A3 in open-access papers:
SLC7A3 is named in the same sentence as 23 diseases in open-access papers, as found by Europe PMC text mining. Sharing a sentence is not in itself a finding about the gene and the disease. The quoted sentences say what the papers report.
osteosarcoma (3 papers, 2017 to 2025). A usually aggressive malignant bone-forming mesenchymal neoplasm, predominantly affecting adolescents and young adults. "Targeting SLC7A3 to inhibit arginine uptake is suggested as a potential therapeutic strategy, especially in the context of osteosarcoma, as SLC7A3 facilitates arginine uptake, which in turn could promote tumor growth and metastasis." (PMID 38204267, 2025). "Within osteosarcoma we identified that cells have higher expression of the SLC7A1 and SLC7A2 amino acid transporters, compared to the SLC7A3 and SLC7A4 transporters consistent with the established role of these isoforms in transporting arginine and other key amino acids such as lysine and ornithine." (PMID 28969007, 2017).
autism (2 papers, 2015 to 2023). Persistent deficits in social interaction and communication and interaction as well as a markedly restricted repertoire of activity and interest as well as repetitive patterns of behavior. "The patient with the most deleterious SLC7A3 variant had high-functioning autism and epilepsy, and also carries a de novo 16p11.2 duplication possibly contributing to his phenotype." (PMID 26215737, 2015). "A single male patient with a deletion of ~93 Mb encompassing SLC7A3 (Decipher ID: 284367) is present in Decipher; interestingly, this patient has a syndromic form of autism and developmental delay with additional dysmorphic and neurologic features." (PMID 26215737, 2015).
autism spectrum disorder (2 papers, 2015 to 2020). A spectrum of developmental disorders that includes autism, and Asperger syndrome. "However, a rare genetic variant of the SLC7A3 has been described in male individuals, and it has been suggested that in association with other genetic factors SLC7A3 variants possibly contribute to the etiology of autism spectrum disorder (ASD) in male subjects." (PMID 33302555, 2020). "In this study, we identified a missense variant in SLC7A3, encoding the CAT-3 cationic amino acid transporter, on chromosome X by exome sequencing in two brothers with autism spectrum disorder (ASD)." (PMID 26215737, 2015).
breast carcinoma (1 paper, 2025). "Kaplan-Meier analyses in various databases consistently demonstrate that higher SLC7A3 expression at diagnosis is associated with better prognosis of breast cancer patients." (PMID 38204267, 2025). "There's a call for further studies to verify the diagnostic and prognostic value of SLC7A3 in breast cancer, indicating a need for more comprehensive research to substantiate initial findings." (PMID 38204267, 2025). "Our analysis indicates an association between high SLC7A3 expression in breast cancer patients and an increased likelihood of lymph node metastasis." (PMID 38204267, 2025). "Kaplan-Meier analysis further supports a closer association between SLC7A3 expression and survival, indicating that higher SLC7A3 expression is predictive of a better prognosis for breast cancer patients." (PMID 38204267, 2025). "The precise mechanisms underlying the association between SLC7A3 expression and survival outcomes in breast cancer patients are yet to be thoroughly explored." (PMID 38204267, 2025). "In this study, we explored the diagnostic and prognostic value of SLC7A3 in breast cancer." (PMID 38204267, 2025). "Our functional experiments, however, indicate that SLC7A3 functions as a cancer suppressor gene, inhibiting the progression of breast cancer." (PMID 38204267, 2025). "This scenario underscores the intricate dual role that SLC7A3 plays in breast cancer development, likely shaped by its interactions with diverse signaling pathways and molecules, thereby engendering varied biological outcomes." (PMID 38204267, 2025). "Our findings indicate a downregulation of SLC7A3 expression in breast cancer tissues compared to adjacent breast tissues." (PMID 38204267, 2025). "Our results consistently demonstrate that SLC7A3 expression is lower in breast cancer tissues than in normal breast tissues." (PMID 38204267, 2025). "SLC7A3 functions as a sodium-independent cationic amino acid transporter, and its expression is higher in normal breast tissue than in breast cancer tissue." (PMID 38204267, 2025). "Subsequent cell experiments are imperative to authenticate the involvement of SLC7A3 in the tumorigenesis and progression of breast cancer, while animal experiments are warranted to establish SLC7A3's viability as a therapeutic target for breast cancer." (PMID 38204267, 2025). "Our forest plot indicates that SLC7A3 expression is positively correlated with overall survival in mesenchymal stem-like breast cancer, reinforcing the notion that SLC7A3 acts as an independent tumor suppressor in breast cancer." (PMID 38204267, 2025). "Our findings align with this observation, as Caucasian breast cancer patients displayed higher levels of SLC7A3 than their African-American and Asian counterparts." (PMID 38204267, 2025). "Our findings contribute to a better understanding of the role of SLC7A3 and its potential applications in breast cancer diagnosis and prognosis." (PMID 38204267, 2025). "This study elucidates the impact of SLC7A3 on the biological attributes of breast cancer cells and the survival prognosis of patients." (PMID 38204267, 2025). "In terms of breast cancer classification, all subtypes of breast cancer exhibit lower SLC7A3 expression compared to normal breast tissue, especially TNBC and HER2-positive breast cancer, which are aggressive breast cancers." (PMID 38204267, 2025). "Our analysis revealed a significant reduction in SLC7A3 expression in all breast cancer subtypes compared to adjacent breast tissues." (PMID 38204267, 2025). "In this study, we conducted a comprehensive bioinformatics analysis using the TIMER, Oncomine, UALCAN, and GEPIA public databases to explore the expression of SLC7A3 in breast cancer compared to normal breast tissue." (PMID 38204267, 2025). "In conclusion, further research is warranted to elucidate the mechanistic underpinnings of SLC7A3 in breast cancer." (PMID 38204267, 2025). "This study unveils a tumor suppressor role of SLC7A3 in breast cancer." (PMID 38204267, 2025).
breast carcinoma (continued). "We analyzed the correlation between the expression of solute carrier family 7 member 3 (SLC7A3), the major arginine transporter, and breast cancer survival in various databases, including GEPIA, UALCAN, Metascape, String, Oncomine, KM-plotter, CBioPortal and PrognoScan databases." (PMID 38204267, 2025). "Our data underscores SLC7A3's function as a tumor suppressor gene in breast cancer." (PMID 38204267, 2025). "This difference in SLC7A3 expression may partially explain the high incidence of breast cancer rates in Asian countries compared to Western countries in recent decades." (PMID 38204267, 2025). "Notably, only SLC7A3 and SLC7A4 showed significant associations with breast cancer patient prognosis." (PMID 38204267, 2025). "The prognostic significance of SLC7A3 in breast cancer patients was thoroughly investigated." (PMID 38204267, 2025). "Moreover, low SLC7A3 expression predicted poor prognosis in breast cancer patients for overall survival." (PMID 38204267, 2025). "High SLC7A3 expression could serve as a prognostic indicator for favorable outcomes in breast cancer patients due to its inhibitory effects on breast cancer cell proliferation and invasion." (PMID 38204267, 2025). "Our research suggests that in late-stage breast cancer, SLC7A3 may play a pro-tumorigenic role." (PMID 38204267, 2025). "Forest plot analysis indicated that SLC7A3 expression is correlated with relapse-free survival in grade 1 but not in grades 2 and 3 breast cancer." (PMID 38204267, 2025). "SLC7A3 is an arginine transporter, a recent study revealed that breast cancer patients with high SLC7A4 expression had better prognoses, while the role of SLC7A3 in breast cancer progression remains unclear." (PMID 38204267, 2025).
breast invasive ductal carcinoma (1 paper, 2025). "The cBioPortal database analysis revealed that approximately 80% of breast invasive ductal carcinoma patients have low SLC7A3 mRNA expression levels, suggesting that reduced SLC7A3 gene transcription may contribute to poor prognosis in this subset of patients." (PMID 38204267, 2025).
Congenital aphakia (1 paper, 2018). Absence of the crystalline lens of the eye as a result of a developmental defect. "For example, the protein product of SLC7A3 is a sodium-independent cationic amino acid transporter associated with congenital aphakia, a rare eye disease characterized by the complete lack of the lens and iris." (PMID 29538408, 2018).
leukemia (1 paper, 2022). A malignant (clonal) hematologic disorder, involving hematopoietic stem cells and characterized by the presence of primitive or atypical myeloid or lymphoid cells in the bone marrow and the blood. "Furthermore, the Slc7a3 deletion does not attenuate leukemia development driven by Pten loss or the oncogenic Ptpn11E76K mutation." (PMID 36528691, 2022). "Our data presented in this report does not suggest that the arginine transporter CAT3 is a useful therapeutic target for controlling cancer cell access to arginine because Pten loss or an oncogenic Ptpn11 mutation-driven leukemia development is not impacted by Slc7a3 depletion." (PMID 36528691, 2022).
lymph node metastasis (1 paper, 2025). "This study bears certain sample biases, particularly the disproportionately low number of N3 patients relative to N0-2 cases, which might skew the analysis regarding the association between SLC7A3 expression and lymph node metastasis." (PMID 38204267, 2025).
meningioma (1 paper, 2025). A generally slow growing tumor attached to the dura mater. "Single-cell analysis revealed that SLC7A1 and SLC7A2 are expressed in meningioma cells, exhibiting mutual exclusivity in expression, while SLC7A3 is barely expressed." (PMID 41184266, 2025).
pancreatic cancers (1 paper, 2025). "Moreover, SLC7A3 is expressed at a low level in both breast and pancreatic cancers compared to normal tissues." (PMID 38204267, 2025).
rhabdomyosarcoma (1 paper, 2017). A rare aggressive malignant mesenchymal neoplasm arising from skeletal muscle. "In rhabdomyosarcomas SLC7A1 and SLC7A4 were strongly expressed, with low SLC7A2 (SLC7A3 not available)." (PMID 28969007, 2017).
thyroiditis (1 paper, 2018). Inflammation of the thyroid gland. "Thyroiditis was significantly correlated with SLC7A2, SLC7A3, SLC7A7, and SLC7A9." (PMID 30558624, 2018).
cancer (7 papers, 2018 to 2025). A tumor composed of atypical neoplastic, often pleomorphic cells that invade other tissues. "SLC7A2 and SLC7A3 encode CAT2 and CAT3 to deliver arginine, which activates mTORC1 to promote cancer cell growth in response to glutamine starvation." (PMID 36313898, 2022). "The different gene effects of SLC7A1, SLC7A2, and SLC7A3 in pan-cancer highlight their distinct molecular functions in tumors, emphasizing the significance of further exploration." (PMID 41184266, 2025). "Furthermore, we analyzed the functional roles of SLC7A1, SLC7A2, and SLC7A3 in pan-cancer using the CRISPR knockout dataset from the DEPMAP portal." (PMID 41184266, 2025). "The results showed that SLC7A1 displayed significantly lower gene effect score compared to SLC7A2 and SLC7A3, suggesting that SLC7A1 plays a more essential biological role in pan-cancer." (PMID 41184266, 2025). "So far, there is no report regarding the involvement of SLC7A3 in cancers, for the first time, our study found that SLC7A3 expression was associated with ETE, higher cancer stage, BRAF, RAS mutation, and mortality in PTC." (PMID 30558624, 2018).
tumor (7 papers, 2018 to 2025). "To determine the possible role of CAT3 (Slc7a3)-mediated arginine uptake in tumor development, we assessed the effect of Slc7a3 deletion on the hematological malignancy driven by Pten loss." (PMID 36528691, 2022). "The modulation of SLC7A3 activity could impact tumor growth, metastasis, and cellular adaptive responses to metabolic stress, thus opening avenues for therapeutic interventions." (PMID 38204267, 2025). "Tumor size was negatively correlated with SLC7A3 mRNA expression." (PMID 30558624, 2018).
infection (5 papers, 2019 to 2024). The state of being infected such as from the introduction of a foreign agent such as serum, vaccine, antigenic substance or organism. "By comparison, mRNA expression of the related cationic amino acid transporter genes, SLC7A2 and SLC7A3, did not change after infection, suggesting that these transporters do not play a major role during Toxoplasma infection." (PMID 31194856, 2019).
SLC7A3 also shares sentences with these, for which no sentence is quoted: glioblastoma (3 papers); glioma (3); developmental delay (1); epilepsy (1); hematological malignancies (1); Intellectual disability (1); juvenile myelomonocytic leukemia (1); papillary thyroid carcinoma (1).